ENSG00000285238 (novel transcript)
Gene: Protein-coding gene on chromosome 12 (6,556,886 to 6,607,367, reverse strand). Ensembl gene ENSG00000285238.
Genetic constraint (gnomAD): Missense variants: 1,115 observed, 2,142 expected, observed/expected ratio (o/e) 0.52, 90% interval 0.5 to 0.55. Synonymous variants: 787 observed, 760.03 expected, observed/expected ratio (o/e) 1.04, 90% interval 0.98 to 1.1.